RNU6-669P (RNA, U6 small nuclear 669, pseudogene)
Gene: Small nuclear RNA gene on chromosome 9 (94,507,738 to 94,507,844, forward strand). Ensembl gene ENSG00000202445.
Homologues: Orthologues: guinea pig U6 (87% identical), pig U6 (83% identical). Paralogues in human: RNU6-621P (93% identical), RNU6-1316P (91% identical), RNU6-41P (91% identical), RNU6-35P (90% identical), RNU6-589P (90% identical), RNU6-797P (90% identical), RNU6-1145P (89% identical), RNU6-12P (89% identical), RNU6-13P (89% identical), RNU6-166P (89% identical), RNU6-188P (89% identical), RNU6-25P (89% identical), and 1284 more.